KMT2A (lysine methyltransferase 2A)
Diseases named in the same sentence as KMT2A in open-access papers (continued):
Sharing a sentence is not in itself a finding about the gene and the disease.
tumor (continued). "In any case, further studies of KMT2A/MLL1, DOT1L and STAT3 dependency across a range of ETS-driven mouse and human tumor models are warranted, particularly with the potential for near-term translational impact using existing clinical-grade inhibitors." (PMID 40858905, 2025). "A study conducted by Yang Fang and colleagues revealed an overexpression of KMT2A in CRC tissues compared with paired paracancerous tissues, with the expression level positively correlated with tumor staging." (PMID 38706918, 2024). "A characteristic feature of tumor cells in TI-related AML is the presence of balanced chromosomal translocations, most often involving the KMT2A gene (also known as MLL) at 11q23.3 and the RUNX1 gene (also known as AML1) at 21q22.1." (PMID 36077220, 2022). "High levels of KMT2A, KMT2C, KMT2E, and KMT2H were shown to be strongly connected with types 3 and 5 infiltrations (C3 and C5), indicating that greater gene expression is linked to a healthy immune system and that these genes may play an important function in tumor suppression." (PMID 35058979, 2022). "It is likely that mutation, activation, and/or overexpression of KMT2A and potentially some of its relatives KMT2B-D may regulate tumour cell growth and proliferation, stemness and self-renewal potential; this may be linked to increased tumour cell plasticity and stemness." (PMID 34944837, 2021). "We also explored the relationship between KMT2A and VDAC1 and their roles in the regulation of tumor growth in a mouse xenograft model." (PMID 32436862, 2020). "As mentioned, KMT2A is essential for the inhibition of cell proliferation and positively regulates NOTCH signaling, suggesting that NOTCH acts as a tumor suppressor in U-87 MG cells." (PMID 28968975, 2017). "The presence or absence of phosphorylation at these sites does not appear to aid or interfere with the ability of menin to interact with KMT2A/D or RNAPII and is supportive of the concept that these tumor mutants are defective in other functions." (PMID 21264250, 2011). "Thus, several lines of evidence from different tumor types and model systems suggest a dependency of ETS-driven malignancies on KMT2A/MLL1 function." (PMID 40858905, 2025). "In view of the structural similarities between DNMT1, and KMT2A we investigated if DEC is able to not only degrade DNMT1 but also KMT2A, possibly revealing a previously unknown DEC‐induced anti‐tumor mechanism." (PMID 39754404, 2025). "Thus, tumors bearing KMT2A–AF4 fusions share a distinct binding profile, but other oncofusion proteins such as KMT2A–ENL and KMT2A–AF9 also appear to be influenced by the lineage bias of the tumor." (PMID 34663924, 2021). "Moreover, we analyzed the relationships of KMT2A/VDAC1 expression with different clinicopathologic variables, and found that the expression of KMT2A and VDAC1 was significantly correlated with the tumor type." (PMID 32436862, 2020). "We demonstrated that KMT2A selectively upregulates different NOTCH receptors, and this mechanism may be crucial for driving NOTCH signaling to be oncogenic or tumor suppressive." (PMID 28968975, 2017). "In addition, nucleophosmin (NPM1m) and meningioma-1 mutations (MN1mut) confer dependency on MEN1 and sensitivity to inhibitors of MEN1–KMT2A interaction despite the non-rearranged KMT2A in these neoplasms." (PMID 38003662, 2023). "FISH studies demonstrated that the tumor was negative for amplification of MDM2 and rearrangements of EWSR1, FUS, and KMT2A." (PMID 34592995, 2021). "Unlike KMT2A and KMT2B, KMT2C and KMT2D are known to impede cell proliferation and, oftentimes, are considered as tumor suppressors." (PMID 33302406, 2020).
tumor (continued). "The close family members of KMT2A, KMT2C, and KMT2D also have negative effects on tumor cell growth, supporting the tumor-suppressive role of the KMT2 family." (PMID 28968975, 2017). "In prior studies, concurrent KMT2A and YAP1 rearrangements were noted in only one tumor tested by both break-apart fluorescence in situ hybridization (FISH) probes; negative FISH results for KMT2A and/or YAP1 were common in cases where the fusion was confirmed by sequencing." (PMID 32461620, 2020). "Interestingly, there was no significant changes between tumor and normal tissue in enzymes writing or erasing H3K4 marks including Kmt2a, Ash1l, Cxxc1, Kdm1a and Ezh2." (PMID 25823816, 2015).
hematologic malignancies (15 papers, 2014 to 2026). "KMT2A is specifically associated with hematologic malignancies due to its crucial role in hematopoietic stem cell (HSC) differentiation." (PMID 41514668, 2026). "Among the KMT2 family (KMT2A–KMT2G), KMT2A is uniquely implicated in hematologic malignancies due to its essential role in hematopoietic stem cell (HSC) differentiation and its propensity for chromosomal rearrangements." (PMID 40361241, 2025). "Compared to structural variations, the occurrence and significance of somatic mutations in KMT2A in hematologic malignancies are less clear." (PMID 39303915, 2024). "In hematologic malignancies, the most common structural variant of KMT2A is the KMT2A-r." (PMID 40361241, 2025). "Additionally, we characterized the predicted KMT2A-CBL protein structure in this case to reveal the underlying leukemogenic mechanisms and summarized reported cases of hematological malignancies with KMT2A::CBL fusion to investigate the correlation of gene rearrangements with clinical outcomes." (PMID 38643442, 2024). "In hematological malignancies, based on shRNA-based knock-down and other proteomic data, BRD4 is correlated with the rearrangement of the mixed lineage leukemia (MLL1) gene (renamed as lysine specific methyl transferase 2A, KMT2A)." (PMID 32218352, 2020).
neurodevelopmental disorder (14 papers, 2019 to 2026). A behavioral and cognitive disorder with onset during the developmental period that involves impaired or aberrant development of intellectual, motor, or social functions. "Recently, de novo KMT2A variants have been identified in sequencing studies of cohorts of individuals with neurodevelopmental disorders (NDDs)." (PMID 31044088, 2019). "In addition, de novo Kmt2a loss-of-function variants were found in people with neurodevelopmental disorders, including ASD." (PMID 34947998, 2021). "Other highly enriched genes for nsDNV—KMT2D (OMIM 147920), KMT2A (OMIM 605130), NSD1 (OMIM 117550), TAB2 (OMIM 614980), and ADNP (OMIM 615873)—have been previously associated with different types of neurodevelopmental disorders with co-occurrence of CHD." (PMID 34324492, 2021).
blood cancer (11 papers, 2017 to 2025). "This is the case of KMT2A, a lysin methyltransferase-coding gene, whose variants are associated with a chromatinopathy (WDSTS) at germinal level or can be found in both blood cancers and solid tumors in regard to malignancies." (PMID 35328068, 2022). "In this study, we used OGM to identify KMT2A PTD across a spectrum of hematological neoplasms." (PMID 39766092, 2024).
infection (9 papers, 2011 to 2025). The state of being infected such as from the introduction of a foreign agent such as serum, vaccine, antigenic substance or organism. "The pathogenesis of infant leukemia involves a prenatal genetic lesion - frequently MLL (KMT2A) gene rearrangement - combined with postnatal events, such as epigenetic dysregulation, aberrant immune responses to infection, or additional somatic mutations that trigger full leukemogenesis." (PMID 40718322, 2025).
genetic disorder (5 papers, 2015 to 2022). "Wiedemann–Steiner syndrome (WDSTS) is a rare genetic disorder characterized by facial gestalt, neurodevelopmental delay, skeletal anomalies and growth retardation, which is caused by variation of KMT2A gene." (PMID 30305169, 2018). "The most common genetic disorders in pediatric AML are rearrangements of the KMT2A (formerly MLL) gene." (PMID 35011701, 2022). "Apart from KMT2A, three other CXXC-domain-containing epigenetic regulators have been linked to Mendelian diseases: KMT2B (DYS28; OMIM:617284), DNMT1 (HSN1E; OMIM:614116), and TET3 (BEFAHRS; OMIM:618798)." (PMID 35727845, 2022).
psychiatric diseases (2 papers, 2019 to 2020). "Interestingly, Kmt2a—a chromatin methyltransferase—mediates its activity specifically at H3K4 and is highly implicated in cellular processes linked to neurodevelopment and psychiatric disorders." (PMID 30283037, 2019).
KMT2A also shares sentences with these, for which no sentence is quoted: lymphoma (14 papers); multiple myeloma (8); chronic myeloid leukemia (6); hepatocellular carcinoma (6); mixed phenotype acute leukemia (6); diabetes (5); diffuse large B-cell lymphoma (5); T-cell acute lymphoblastic leukemia (5); alveolar rhabdomyosarcoma (4); breast tumor (4); chronic lymphocytic leukemia (4); Cognitive impairment (4); hematological cancers (4); Hyperglycemia (4); liver cancer (4); neuroblastoma (4); adenoma (3); anemia (3); Burkitt lymphoma (3); endometrial cancer (3); lung adenocarcinoma (3); monocytic leukemia (3); non-small cell lung carcinoma (3); Sepsis (3); triple-negative breast carcinoma (3); adenocarcinoma (2); astroblastoma (2); Ataxia (2); autism spectrum disorder (2); carcinoid (2).
A further 122 diseases each share a sentence with KMT2A in 2 papers or fewer.